IL33 (interleukin 33)
Diseases named in the same sentence as IL33 in open-access papers (continued):
Sharing a sentence is not in itself a finding about the gene and the disease.
asthma (continued). "Moreover, recent studies have shown that IL-33 is involved in asthma airway collagen deposition, suggesting that IL-33 may be involved in the EMT process in the lung." (PMID 32793232, 2020). "The IL-33 pathway has critical importance in type two immune responses both in allergy and helminth parasite ejection, thus it could be a central factor in parasite immunomodulation and the prevention of asthma." (PMID 32420871, 2020). "There are also compelling data relating the innate immune system to later asthma and atopy, and animal studies suggest that the effects of a high endotoxin, microbiologically diverse environment may be modulated via the epithelial alarmin IL-33." (PMID 30941335, 2019). "Angiogenesis is a feature of airway remodeling in asthma, and it has been demonstrated that IL-33 can increase the expression of blood vessel von Willebrand factor (vWF), as well as angiogenic factors such as angiogenin when administered nasally to a murine asthma surrogate model." (PMID 31293586, 2019). "Interestingly, genome-wide association studies of asthma have identified RORα (a critical transcription factor for ILC2 development), as well as TSLP, IL-33 and the IL33-receptor (IL1RL1, ST2) as asthma susceptibility genes, supporting the importance of this pathway for asthma." (PMID 31024538, 2019). "Since most of previous studies on IL-33 blocking agents are at the stage of in vitro and animal testing, pharmacological evaluations to develop IL-33–blocking agents are still on-going and some are in phase I–II clinical trials for asthma and chronic obstructive pulmonary disease." (PMID 30886621, 2019). "Finally, we provide in vivo evidence that our findings of reciprocal regulation between IL-33 and Glrx may be involved in a mouse model of asthma." (PMID 30682073, 2019). "Furthermore, in animal models, exogenous administration of IL-33 causes airway hyperresponsiveness (AHR), a canonical feature of asthma, and studies using IL-33 deficient or ST2 deficient mice indicate that IL-33 contributes to both allergic and virally-induced AHR." (PMID 31455422, 2019). "Although not conclusive due to these eQTLs being observed in tissues not directly relevant to asthma or lung function, these results suggest that Il33 could represent at least one of the candidate causal genes at the chromosome 19 locus." (PMID 31869344, 2019). "In this study, we identified pLOF variants that protect against obesity (GPR151), asthma (GSDMB, IL33), autoimmune disorders (IFIH1), and coronary artery disease (PDE3B), prioritizing genes and pathways for which pharmacologic attempts to mimic these protective mutations might ameliorate disease." (PMID 29691411, 2018). "In addition, IL-33-mediated Th2 polarization and AHR may be the mechanisms underlying pediatric severe asthma with fungal sensitization." (PMID 29987222, 2018). "Thus, the potent ability of the herein established IL-33-IRAK-M-PIN1 axis to induce this set of pro-inflammatory cytokines may contribute to their critical roles in asthma." (PMID 29686383, 2018). "Elevated production of IL-33 by damaged or stressed cells of the barrier epithelium could promote airway hyper-responsiveness and development of inflammatory response during the initiation and persistence of asthma." (PMID 30257479, 2018). "However, IL-33 was not required during challenge in the lungs, indicating that targeting IL-33 signaling pathway during AD development might offer a new therapeutic insight in the prevention of asthma." (PMID 28490737, 2017). "In the case of IL33, all asthma-associated SNPs in this region of the genome are located in the 5′ or first intron of IL33, and eQTL analysis has revealed that SNPs in the promoter region of IL33 are correlated with IL-33 expression in bronchial epithelial cells." (PMID 28583446, 2017).
asthma (continued). "Recently the genes encoding IL-33 and ST2 (also known as interleukin-1 receptor-like 1, IL-1RL1), have been identified as important factors for human asthma in several genome-wide association studies that included thousands of patients from diverse ethnic groups having different forms of asthma." (PMID 27310495, 2016). "The increase in IL-33 in nasal aspirates from infants along with our mouse data cumulatively suggest that IL-33 and ILC2s are critical for the age-dependent development of asthma following severe RSV infection during infancy and that they may be a plausible therapeutic target." (PMID 26473724, 2015). "Therefore, IL-33 might be an important novel therapeutic target to modulate mast cell–ASM crosstalk in asthma." (PMID 25683166, 2015). "Exacerbations of asthma might in part be driven by IL-33, e.g., through its action on mast cells, why administration of this type of cytokine vaccine may prove to be an effective therapeutic tool for treating allergic asthma, as well as other phenotypes of asthma where IL-33 also are implicated." (PMID 26214807, 2015). "We hypothesize that the IL-33/ST2 axis plays a role in mast cell–ASM interactions in asthma." (PMID 25683166, 2015). "Moreover, increased airway epithelial IL-33 protein expression was found in severe asthma." (PMID 24822215, 2014). "Thus, airway epithelial cells are also active players in the pathogenesis of asthma through epithelial cytokines including IL-33, TSLP, and IL-25, which are produced and released by epithelial cells in response to various exogenous stimuli or by cellular damage." (PMID 23496815, 2013). "IL-33 may be involved in lung macrophage activation in clinical asthma and may play a significant role in the amplification of alternatively activated macrophage (AAM) polarization and chemokine production, which contribute to both innate and Ag-induced airway inflammation." (PMID 20671916, 2010). "Serving as a foundational element in asthma therapy, TNF can interact with TNF-like ligands and IL33 to trigger allergic airway inflammation, which has also been regarded as a marker for allergic pulmonary disorders." (PMID 40420184, 2025). "In the obese asthma model, FIP-fve markedly attenuated Der p-induced AHR and decreased serum levels of pro-inflammatory and allergic markers, including IL-6, IL-33, osteopontin, and VCAM-1." (PMID 40998975, 2025). "It has been found that levels of IL-33 and ST2 receptor were elevated in groups characterized by uncontrolled asthma symptoms and low eosinophilia." (PMID 41156007, 2025). "In typical Th2‐high phenotype asthma, airway epithelium interacts with environmental factors to induce innate and adaptive immune and inflammatory responses, releasing TSLP, IL‐33, and IL‐25." (PMID 39800672, 2025). "We have reported that ILC2 are more activated by IL-33 in female mice as compared to male mice, and others have shown more ILC2 in females with severe asthma compared to males with severe asthma." (PMID 40821845, 2025). "Air pollutants contribute by activating type 2 pathways, promoting epithelial cytokine release (IL‐33 and TSLP), oxidative stress, and pro‐inflammatory mediators (IL‐6, IL‐8, and IL‐1β) relevant to asthma." (PMID 40679787, 2025). "More recently, clinical therapies are under development for neutralizing IL-33 and the IL-33 receptor subunit, ST2, in patients with uncontrolled and severe asthma and in atopic dermatitis." (PMID 40821845, 2025). "Furthermore, studies suggest that virus-induced asthma exacerbations may be associated with an impaired innate immune response to RV, especially by interferon I and III pathways, thymic stromal lymphopoietin, and the IL-33 proteins." (PMID 39507925, 2025). "Clinically, IL-33 and ST2 levels are elevated in the serum and sputum of asthma patients and correlate with disease severity." (PMID 41169790, 2025).
asthma (continued). "IL-33, acting on ST2 receptors on Th2 lymphocytes, directly stimulates their chemotaxis and differentiation, thus contributing directly to asthma pathogenesis." (PMID 41246133, 2025). "Key triggers for mast cell activation in asthma include allergen-stimulated IgE receptors (FCεRI), toll-like receptors, and cytokines that activate alarmin receptors (e.g., TSLP, IL-33)." (PMID 40443529, 2025). "Inhibition of IL-33 is being explored as a potential therapy for COPD, while IL-25 is being targeted in asthma and idiopathic pulmonary fibrosis." (PMID 41409758, 2025). "Specifically, IL-37 can alleviate asthma by inhibiting Th2/Th17 immune responses, inhibiting the release of epithelial-derived alarmins (TSLP and IL-33), and attenuating airway remodeling." (PMID 41293155, 2025). "It is clearly that the epithelial and epidermal derived alarmins IL-25, IL-33, and TSLP play crucial roles in the action of allergic inflammation in asthma and AD." (PMID 40236701, 2025). "In contrast to T2-high asthma, epithelial-derived alarmins such as IL-33, IL-25, and TSLP play a less prominent role in T2-low asthma." (PMID 40806756, 2025). "Aeroallergen exposure can trigger ATP/ADP release, activating purinergic receptors (like P2Y1) on epithelial cells to induce IL‐33 and HMGB1 release, contributing to asthma pathogenesis." (PMID 40679787, 2025). "In children with asthma, TSLP, IL-25 and IL-33 are recognized as key epithelial mediators that define the T2-high endotype and have been highlighted as potential therapeutic targets and biomarkers of disease activity." (PMID 40981017, 2025). "Future investigations should focus on profiling IL‐33 on sputum and/or airway biopsies of patients with COPD and asthma, with an emphasis on distinguishing IL‐33 levels across different pheno‐endotypes." (PMID 40492692, 2025). "Baseline total IL-33 levels in serum were typically undetectable in both healthy subjects and those with asthma, mirroring findings in COPD populations with low systemic IL-33 concentrations." (PMID 40732309, 2025). "During the course of both diseases, IL-25, IL-33, and TSLP cytokines are notably increased, which are all substantial in provoking a pathological immunologic response, proven in a mouse asthma model, and TSLP alone in a mouse AD model." (PMID 40149608, 2025). "In patients with asthma, NMU activates ILC2 more rapidly than IL-33, highlighting the importance of the NMU–NMUR1 pathway in the early activation of ILC2." (PMID 40305320, 2025). "IL-33 is elevated in the epithelial cells and bronchoalveolar lavage (BAL) fluid of individuals with asthma and is clearly correlated with the severity of the disease." (PMID 39060923, 2024). "Sputum IL-25 is greater in obese as compared to lean asthmatics while BAL IL-33 and TSLP are greater in obese as compared to lean mice with experimental asthma." (PMID 38878250, 2024). "The aim of this study was to analyze the involvement of IL-33 and TSLP in pediatric asthma, exploring their role in children with mild asthma." (PMID 38731070, 2024). "It appears that there is a necessity for a more detailed characterization of IL-33/ST2-dependent mast cell responses and their relevance in the context of asthma." (PMID 38731070, 2024). "Our findings indicate that several cytokines, including IL-5, IL-17A, IL-22, IL-33, TNF-α, leptin, and IL-10 were independently influenced by asthma and obesity." (PMID 39902293, 2024). "Small molecule inhibitors, such as JAK-inhibitors, and monoclonal antibodies targeting mast cells, IL-1, IL-6, IL-33, TNFα, and OX40L are under investigation for their potential to modulate inflammation involved in refractory asthma." (PMID 39194521, 2024). "In our study, calycosin was capable of reducing the levels of IL-33 and ST2 to inhibit ILC2 activation in asthma." (PMID 38650035, 2024).
asthma (continued). "The IL-33/IL1RL1 pathway plays a crucial role in host defense and in the pathogenesis of immune-mediated, allergic, and chronic inflammatory diseases such as asthma, dermatitis, arthritis, and Alzheimer’s disease." (PMID 39595128, 2024). "Overall, our study suggests asthma patients carrying the extracellular and TIR domain risk haplotype and have a lung microenvironment that promotes elevated levels of cleaved IL33, particularly where IL3395–270 and IL33106–270 may be more amenable to IL33/IL1RL1 targeting." (PMID 39301832, 2024). "Even because, in a chronic model of asthma induced by OVA, IL-33 was able to stimulate fibroblasts to secrete type I collagen." (PMID 38666018, 2024). "Genome-wide association studies and successful phase 2/phase 3 clinical trials support the critical role of IL-33 and TSLP in human asthma." (PMID 38597952, 2024). "Research has shown that prophylactic or therapeutic administration of P2Y13-R, also known as IL-33 and High-mobility group box1 (HMGB1)’s novel gatekeeper, in experimental asthma models can attenuate the onset and progression of asthma." (PMID 39301028, 2024). "Elevated levels of TSLP, IL-25, IL-33 and the IL-33 receptor serum stimulation-2 (ST2) in the serum and bronchial tissue of patients with asthma have also been found to correlate with T2 inflammation and disease severity." (PMID 38453256, 2024). "The type 2 inflammation in asthma is initiated by ‘alarmin cytokines’ such as TSLP, IL-25, and IL-33 secreted by BECs when sensitized by allergens." (PMID 38641850, 2024). "Specifically, the monoclonal antibodies itepekimab and astegolimab (both targeting IL-33 and its receptor ST2) have shown promising results in reducing asthma exacerbations and airway inflammation." (PMID 39767672, 2024). "They empress pattern recognition receptors that detect the stimuli and secrete “alarmin cytokines” including IL-25, IL-33 and TSLP, which contributes to the pathogenesis of asthma." (PMID 38641850, 2024). "Thirdly, although we found that the cytokines or markers, such as IL-33, ST2, IL-4 and MRC1, participated in the treatment of calycosin in asthma, the direct molecular mechanism of action is still unclear." (PMID 38650035, 2024). "Downstream, IL33 can interact with its receptor (ST2) to initiate a cascade of mediators leading to asthma, including T-helper 2 (T2) cell-mediated asthma, non-T2 asthma and mixed asthma." (PMID 39337527, 2024). "In asthma, airway remodeling requires EMT, and exposure to HDM extract leads to increased expression of IL-33 in alveolar epithelial cells." (PMID 38898476, 2024). "Epithelium-derived factors (TSLP, IL-33, CCL2) are also known to induce DC migration and maturation, especially of moDCs in severe asthma." (PMID 39244793, 2024). "Epithelium-derived cytokines or alarmins, such as interleukin-33 (IL-33) and thymic stromal lymphopoietin (TSLP), are major players in type 2 immunity and asthma." (PMID 38597952, 2024). "Paradoxically, the genetic ablation of IL-33 leads to asthma and cardiac hypertrophy; at HNLD and LD10 doses in this study, cardiac IL-33 was still significantly decreased at day 7, suggesting a long-term impact warranting further elucidation." (PMID 39065791, 2024). "As previously discussed, in stable type 2-high asthma, the airway epithelium releases TSLP, IL-25, and IL-33, differentiating DC-activated TH2 cells." (PMID 39439788, 2024). "In a novel mechanistic study using samples from patients with uncontrolled asthma in the randomised, double-blind, placebo-controlled phase 2 UPSTREAM trial, tezepelumab decreased production of IL-33 in bronchoalveolar lavage at 12 weeks." (PMID 39694589, 2024). "We investigated the effect of BT on the epithelial expression of the trio of alarmins IL-25 and IL-33 and TSLP which are well documented in asthma as well as on hBD2, an antimicrobial peptide." (PMID 37996952, 2023).
asthma (continued). "Mediators, which are derived from epithelial cells of the airways (AECs), include cytokine alarmins such as IL-25, IL-33, and thymic stromal lymphopoietin (TSLP), which have arisen as crucial elements in the pathogenesis of asthma." (PMID 37685567, 2023). "In contrast with blockage alone, the combined blockade of IL-25, IL-33, and TSLP has been shown to further inhibit airway remodeling and inflammation in a mouse model of asthma." (PMID 38082335, 2023). "have identified intelectin (ITLN) knockdown suppressed expression of IL-33, IL-25, and TSLP expression in asthma and atopic dermatitis models." (PMID 37153553, 2023). "IL-25, IL-33, and TSLP were identified as the principal regulators of type 2 immunity in patients with allergic disease and asthma in recent years." (PMID 36674744, 2023). "An increase in IL-33 in airway epithelium and BAL fluid correlated with the severity of asthma patients." (PMID 36832296, 2023). "Currently, there has been an influx of biologic treatments for asthma targeting cytokines that are notable drivers for asthma exacerbation, such as tezepelumab (anti-TSLP), astegolimab (anti-ST2), itepekimab (anti-IL-33), and risankezumab (anti-IL-23)." (PMID 37377967, 2023). "Our finding that montelukast increased IL25, IL33, and TSLP expression supports the reduced effectiveness of LTRAs in terms of the clinical outcomes of asthma." (PMID 36674744, 2023). "NFκB1 was critical for IL33 production, ILC2 generation, and production of type-2 cytokines, which resulted in eosinophilic inflammation and other features of asthma." (PMID 37575259, 2023). "The researchers found that DEP-induced IL-25, IL-33, and TSLP expression was increased in primary bronchial epithelial cells from patients with mild asthma through the aryl hydrocarbon receptor and increased levels of acetyl-histone H3." (PMID 36674744, 2023). "With an emphasis on the role of IL-33 in COPD, some biologics used to treat asthma have been tested in COPD." (PMID 38082335, 2023). "This study confirmed the significant role of IL-33 and HMGB1 in neutrophilic asthma and suggested that Lip-1 reduced asthma by blocking ferroptosis." (PMID 36675299, 2023). "IL-33 induces the expression of fucosyltransferase 2 (Fut2), and glycation of BECs leads to sustained ILC2 activation in T2 asthma." (PMID 38203353, 2023). "Although the role of omentin in dengue is not known, omentin (intelectin) was shown to induce allergen induced production of IL-25, IL-33 and TSLP in asthma and atopic dermatitis." (PMID 37676889, 2023). "Here, CpG-ODN administration markedly downregulated IL-33/ST2 and decreased inflammation in the smoke-related asthma model induced by the adoptive transfer of DCs." (PMID 36834541, 2023). "The epithelium-derived cytokines interleukin (IL)-25, IL-33, and thymic stromal lymphopoietin (TSLP) are important mediators that initiate innate type 2 immune responses in asthma." (PMID 36674744, 2023). "Here, we found that deficiency of PTRF could reduce lung IL-33, ZBP1, phosphor-receptor-interacting protein kinase 3 (p-RIPK3), and phosphor-mixed lineage kinase domain-like (p-MLKL) (necroptosis executioner), and airway inflammation in an HDM-induced asthma mouse model." (PMID 37454215, 2023). "It targets alarmins, which are key epithelial inflammatory cytokines involved in the pathogenesis of asthma, and is a novel group of antibodies (TSLP, IL-25, and IL-33)." (PMID 38203353, 2023). "We also evaluated by qRT-PCR the effect of BT on the expression of IL-25, IL-33, TSLP and hBD2; typical asthma-related alarmins or antimicrobial peptides in BECs." (PMID 37996952, 2023). "SA ILC2s demonstrated a 100‐fold increased release of IL‐6 following stimulation with IL‐2, IL‐33, IL‐25 and TSLP compared to mild asthma and the controls." (PMID 37114915, 2023).